DAB2IP (DAB2 interacting protein)
Diseases named in the same sentence as DAB2IP in open-access papers (continued):
Sharing a sentence is not in itself a finding about the gene and the disease.
hepatocellular carcinoma (20 papers, 2013 to 2024). A malignant tumor that arises from hepatocytes. "Notably, our group’s previous work demonstrated that EZH2, an upstream inhibitory regulatory protein of DAB2IP, serves as a promising diagnostic biomarker for hepatocellular carcinoma and supports nasopharyngeal carcinoma cell aggressiveness." (PMID 35248066, 2022). "Stable expression of these circRNAs reduced the capacity of CSC-like keratinocytes and hepatocellular carcinoma cells to form colonies, invade, migrate, and generate tumors in nude mice; this correlated with upregulation of endogenous DAB2IP." (PMID 38902547, 2024). "For example, in hepatocellular carcinoma, circRNA-5692 enhances DAB2IP (DAB2 interacting protein) expression through sponging miR-328-5p, thereby inhibiting the development of hepatocellular carcinoma." (PMID 35440286, 2022). "Recently, there has been increasing evidence that reduced expression of DAB2IP occurs in several types of human malignancies, including prostate cancer, lung cancer, hepatocellular carcinoma, renal cancer, and breast cancer." (PMID 35248066, 2022). "circRNA-5692 attenuates the malignant behaviors of hepatocellular carcinoma by suppressing the miR-328-5p/DAB2IP axis." (PMID 35712504, 2022). "In hepatocellular carcinoma, circRNA-5692 inhibits the progression of hepatocellular carcinoma by enhancing DAB2IP expression through sponge miR-328-5p." (PMID 34938350, 2021). "For example, circRNA-5692 binds to miR-328-5p to enhance DAB2IP expression and thus inhibits cell migration, proliferation, and invasion in hepatocellular carcinoma." (PMID 33154193, 2020). "A similar regulatory loop has been described in hepatocellular carcinoma, where DAB2IP mRNA and protein levels were upregulated upon overexpression of circ-5692, able to sponge the DAB2IP-targeting miR-328-5p." (PMID 33096593, 2020). "The hypoxia-inducible miR-182 was reported to target two different RasGAPs: RASA1 in hepatocellular cancer and oral cavity squamous cells carcinoma, and DAB2IP in colorectal carcinoma." (PMID 33096593, 2020). "We further raised that low expression of DAB2IP contributed to malignant development and poor prognosis in hepatocellular carcinoma." (PMID 26336990, 2015). "Down-regulation of DAB2IP results in cell proliferation and invasion in bladder cancer and hepatocellular cancer." (PMID 26336990, 2015). "DAB2IP is known as a tumor suppressor in several cancers, such as breast, lung and hepatocellular carcinoma." (PMID 25115390, 2014). "Furthermore, low levels of DAB2IP were detected in a hepatocellular carcinoma subclass from patients with poor survival." (PMID 26471467, 2015). "Down-regulation of DAB2IP results in cell invasion in bladder cancer and hepatocellular cancer." (PMID 26336990, 2015). "In hepatocellular carcinoma cells (HCC), miR-1307-3p increased proliferation and invasion under hypoxia conditions by downregulating DAB2IP to activate AKT/mTOR and increase HIF-1α expression." (PMID 38902547, 2024). "Demethylation of DAB2IP gene weakened the EMT process and suppressed hepatocellular carcinoma growth." (PMID 34956313, 2021).
colorectal cancer (14 papers, 2014 to 2025). A primary or metastatic malignant neoplasm that affects the colon or rectum. "Whereas PRRT2 mutations were also frequent in both colorectal, endometrial and ovarian cancer cell lines DAB2IP mutations were mostly restricted to prostate and colorectal cancer samples." (PMID 27907910, 2017). "Almost identical observations were reported in colorectal cancer, where the expression of DAB2IP sensitized cancer cells to cisplatin, oxaliplatin, and doxorubicin, and inhibited tumor growth in mouse xenografts, with reduced AKT and ERK activation." (PMID 38902547, 2024). "Several studies investigated the role of DAB2 and its interactive protein (DAB2IP) in colorectal carcinoma." (PMID 37510211, 2023). "A liver metastasis model of colorectal cancer was used to determine the role of DAB2IP in tumor metastasis in vivo." (PMID 26564738, 2015). "A previous study showed that efficient downregulation of DAB2IP could activate the MEK/ERK signalling pathway in colorectal cancer." (PMID 40263693, 2025). "Similarly, miR-182 targets DAB2IP and expression of an anti-miR-182 inhibited colorectal cancer growth in vivo by upregulating DAB2IP." (PMID 38902547, 2024). "In colorectal cancer cells, phosphorylation by Akt1/2 on Smurf1 Thr145 augments Smurf1 protein stability to control DAB2IP abundance, which contributes to increased ubiquitination and degradation of tumor suppressor DAB2IP, dampening DAB2IP’s inhibitory effect on tumor cells." (PMID 33718111, 2020). "Previous studies have reported that the downregulation of DAB2IP can activate the MEK/ERK signalling pathway, promoting the malignant progression of colorectal cancer." (PMID 40263693, 2025). "More recently, the same group reported that in a fraction of colorectal cancers DAB2IP is mutated or silenced regardless of RAS or BRAF mutation, strongly indicating that DAB2IP loss-of-function may provide aggressive phenotypes independently of RAS hyperactivation." (PMID 38902547, 2024). "Then, a series of in vitro and in vivo experiments were conducted to reveal the role of DAB2IP and HSP90AA1 in the invasion and metastasis of colorectal cancer, and flow cytometry was used to explore their effects on apoptosis." (PMID 35590292, 2022). "For instance, inhibition of DAB2IP promoter methylation via knockdown of the DNA methyltransferase 3A (DNMT3A) reduced proliferation and survival of colorectal cancer cells by counteracting the activation of the MEK/ERK signaling pathway, possibly as a consequence of increased DAB2IP levels." (PMID 38902547, 2024). "In colorectal cancer, miR-889 may be involved in controlling the proliferation of CRC by regulating DAB2IP, which provides potential and potential therapeutic targets for colorectal cancer." (PMID 34116691, 2021). "DAB2IP has been identified as a tumor suppressor in several cancers but its oncogenic role and transcriptionally regulatory mechanisms in the progression of colorectal carcinoma (CRC) remain unknown." (PMID 26336990, 2015). "DAB2IP also acts as a negative modulator of HSP90AA1 in colorectal cancer; through an unknown mechanism, DAB2IP inhibits HSP90AA1-mediated upregulation of SRP9, fostering activation of the pro-apoptotic JNK/ASK1 pathway and counteracting metastasis." (PMID 38902547, 2024). "However, the specific regulatory mechanism of DAB2IP and HSP90AA1 in colorectal cancer (CRC) is not clear." (PMID 35590292, 2022). "However, the role of DAB2IP in regulating CSC features and its clinical implication in colorectal cancer has not been determined." (PMID 26564738, 2015).
bladder cancer (12 papers, 2015 to 2024). "Regarding radiotherapy, DAB2IP loss promotes bladder cancer cells resistance to ionizing radiation (IR) by increasing the expression of ataxia‐telangiectasia mutated (ATM) and the activation of NF-κB pathway and p38MAPK." (PMID 38902547, 2024). "The radiation resistance of DAB2IP deficient bladder cancer translates into worse cancer‐specific survival." (PMID 26471467, 2015). "In bladder cancer, DAB2IP overexpression was reported to reduce metastasis and chemoresistance in vitro by inhibiting STAT3 activation." (PMID 38902547, 2024). "In bladder cancer, estrogen receptor β (ERβ) increases transcription of miR-92a, consequently decreasing DAB2IP levels and promoting cancer growth and invasion." (PMID 33096593, 2020). "In early studies with prostate and bladder cancer cell lines, DAB2IP knockdown increased resistance to ionizing radiation but rendered them sensitive to combined treatment with genotoxic drugs such as the bacterial cytolethal distending toxin (CdtB) or an ATM inhibitor." (PMID 38902547, 2024). "Another study showed that elevated ATM expression, induced by DAB2IP-knockdown [disabled homolog 2 interactive protein (DAB2IP)—a tumor suppressor gene] might represent a key event in bladder cancer radioresistance." (PMID 33224881, 2020). "In addition, DAB2IP can also be a down-stream target of miR-92b in bladder cancer cells to facilitate EMT and promote tumor cell migration or invasion." (PMID 33344221, 2020). "A previous study suggested that Estrogen receptor β could increase the levels of miR-92a by binding to the estrogen-response-element (ERE) leading to a decrease in DAB2IP tumor suppressor expression to ultimately promote bladder cancer growth and invasion." (PMID 31827401, 2019). "Improving chemotherapy response could improve survival in this population as patients with reduced DAB2IP in bladder cancer treated with surgery and adjuvant chemotherapy had worse cancer‐specific survival." (PMID 26471467, 2015). "In addition to its role in PCa, down-regulation of DAB2IP increased cell proliferation and invasion in bladder cancer." (PMID 26587829, 2015). "Intriguingly, miR-556 was detected in the plasma of bladder cancer patients, suggesting that this miRNA could repress DAB2IP in a cell non-autonomous manner." (PMID 33096593, 2020).
lung carcinoma (9 papers, 2011 to 2021). "In a case-control study of 1056 lung cancer cases and 1056 sex and age frequency-matched cancer-free controls, we investigated the association between two common polymorphisms in DAB2IP gene (−1420T>G, rs7042542; 97906C>A, rs1571801) and the risk of lung cancer." (PMID 22046421, 2011). "Taken these together, we hypothesized that the genetic variations in DAB2IP gene and their possible interactions with environmental factors are associated with the risk of lung cancer." (PMID 22046421, 2011). "We further performed Cox regression analysis with and without adjustments for sex, age, smoke status, drink status and BMI, and found that the genetic variant 97906A (97906CA and AA) of DAB2IP was an independent factor for the early onset of lung cancer patients (P = 0.033, Pad = 0.031)." (PMID 22046421, 2011). "Since DAB2IP involves in the development of lung cancer and low expression of DAB2IP are observed in lung cancer, we hypothesized that the variations in DAB2IP gene can increase the genetic susceptibility to lung cancer." (PMID 22046421, 2011). "In this lung cancer case–control study in a southern Chinese population, we investigated association between two common variants of DAB2IP and the risk of lung cancer with a relatively large sample size of 1056 lung cancer patients and 1056 cancer-free controls." (PMID 22046421, 2011). "Because of the critical role of DAB2IP in the etiology of lung cancer, here we found that the 97906C>A SNP was also associated with an increased risk of lung cancer in males; it suggests that the 97906A variants may play an important role in etiologic of lung cancer." (PMID 22046421, 2011). "In“in vitro” experiments we studied the effect of cigarette smoke extract (CSE) on EZH2/H3K27me3/DAB2IP expression, apoptosis, invasiveness, and vimentin expression in 16HBE, primary cells, and lung cancer cell lines (A549) long-term exposed to CSE." (PMID 31666665, 2019). "In conclusion, the cellular and molecular mechanisms associated to EZH2 and DAB2IP regulation represent a potential link between chronic inflammation and COPD progression towards lung cancer." (PMID 31666665, 2019). "The habit of cigarette smoking alters the balance of the expression of these markers, promoting molecular events triggering epigenetic modification of DAB2IP oncogene, promoting the progression of inflammatory disease towards lung cancer." (PMID 31666665, 2019). "Due to the aberrant methylation in the DAB2IP promoter region, low expression of DAB2IP was found in several types of cancer including lung cancer, and increased level of DAB2IP can suppress cancer growth." (PMID 22046421, 2011). "The mRNA levels of DAB2IP in 32 lung cancer tissues were significantly lower than their adjacent normal tissues (P<0.001)." (PMID 22046421, 2011). "We amplified the fragment of DAB2IP/MLL fusion gene with PCR method as von Bergh AR described for all of those 82 lung cancer tissues and their adjacent normal tissues." (PMID 22046421, 2011). "RASSF1A and DAB2IP are frequently suppressed by promoter hypermethylation in lung cancer." (PMID 33348649, 2020). "In this scenario we concluded that the habits to cigarette smoke might promote epigenetic modifications of EZH2/H3K27me3/DAB2IP, which the onset of pathogenic mechanisms of COPD, persist even after smoking cessation, encouraging the progression of inflammation toward lung cancer." (PMID 31666665, 2019). "The impaired expression of these markers might generate the abnormal cell proliferation in the area of metaplastic epithelium, suggesting a potential involvement of EZH2/H3K27me3/DAB2IP pathway in the progression of inflammatory diseases of the airways toward lung cancer." (PMID 31666665, 2019). "Studies have found that smoking can affect the expression of EZH2 through reduced DAB2IP via H3K27me3 in COPD patients and promote the transformation of COPD into lung cancer." (PMID 33299862, 2020).
lung carcinoma (continued). "However, we failed to observe the DAB2IP/MLL fusion gene in 82 cases of lung cancer tissues and their adjacent normal tissues, let alone the possible effect of 97906C>A polymorphism on DAB2IP/MLL fusion gene." (PMID 22046421, 2011).
renal cell carcinoma (7 papers, 2015 to 2024). "A recent study also showed the loss of DAB2IP gene expression in different subtypes of renal cell carcinoma." (PMID 26587829, 2015). "DAB2IP is one of the members of Ras GTPase superfamily implicated in the regulation of cell metastasis, apoptosis, and proliferation; it also has been associated with immune cell infiltrates in renal cell carcinoma." (PMID 36561735, 2022). "As the effector cells of tumor immunotherapy, CD8 + T cells help renal cell carcinoma spread by blocking the DAB2IP signaling pathway, which is a tumor suppressor gene." (PMID 38600527, 2024). "Similarly, renal cell carcinoma cells with low DAB2IP levels are resistant to IR but specifically sensitive to treatment with radiotherapy plus PARP inhibitors." (PMID 38902547, 2024). "Consistently, DOC-2/DAB2 interactive protein (DAB2IP) can form a complex with PARP-1 and its identified E3 ligase in renal cell carcinoma (e.g., RanBP2, TRIP12, RNF40, and VHL), leading to PARP-1 degradation." (PMID 36694209, 2023).
colon carcinoma (6 papers, 2015 to 2025). "Of note, DAB2IP was found to be upregulated by ubenimex in a high-throughput mass spectrometry survey of drug effects in colon cancer cells (DeepCoverMOA,), an observation that indirectly validates our screening approach." (PMID 40867592, 2025). "Zhang and colleagues reported that colon cancer cells grown in a soft fibrin matrix significantly reduce DAB2IP levels, and this correlates with Nanog upregulation and enhanced proliferation and self-renewal, both in vitro and in mouse xenografts." (PMID 38902547, 2024). "More recently, Cichowski and colleagues elegantly showed that loss of DAB2IP triggers the production of inflammatory mediators and the onset of a pro-tumorigenic immune microenvironment in KRAS-mutant colon cancer." (PMID 38902547, 2024). "In contrast to the activated PI3K/AKT pathway, the MAPK family number JNK was inactivated and could be recovered upon DAB2IP overexpression in 3D colon cancer cells." (PMID 30770783, 2019). "We investigated the differences in the expression of DAB2IP, HSP90AA1 and SRP9 among different subtypes of CMS classification in colon cancer." (PMID 35590292, 2022). "In this study, we showed the critical role of NF-κB in DAB2IP modulation of EMT and CSC in colon cancer cells." (PMID 26564738, 2015).
glioma (6 papers, 2012 to 2025). A benign or malignant brain and spinal cord tumor that arises from glial cells (astrocytes, oligodendrocytes, ependymal cells). "For instance, DAB2IP deficiency was found to upregulate Wnt‐mediated NLGN3 secretion, which in turn transformed neighboring glioma cells into cancer stem cells (CSCs) and contributed to tumor aggressiveness." (PMID 40589077, 2025). "Analysis of The Cancer Genome Atlas (TCGA) database, low-grade glioma including grade I pilocytic through grade III anaplastic patients expressed significantly higher levels of DAB2IP mRNA than high-grade GBM patients." (PMID 37443071, 2023). "Similarly, DAB2IP knockdown led to increased RELB binding to TMEM147, which is known to regulate cell proliferation, and PSENEN, a prognostic marker in low-grade gliomas." (PMID 39418101, 2024).
ovarian carcinoma (6 papers, 2017 to 2024). A malignant neoplasm originating from the surface ovarian epithelium. "They revealed that the absence of Smurf1 represses cell proliferation, invasive capability, and EMT process in ovarian cancer through DAB2IP/AKT/Skp2 signaling loops." (PMID 35654587, 2022). "Differentially expressed in ovarian carcinoma 2/disabled-2 (DOC-2/DAB2 or DAB2IP) is also known as ASK1-interacting protein-1, a novel member of the Ras GTPase-activating protein family." (PMID 30602706, 2018). "Notably, deletion of SMURF1 in ovarian cancer cells increased DAB2IP levels and reduced proliferation, invasion and EMT; depletion of DAB2IP restored proliferation and EMT in SMURF1-knockout cells, suggesting that SMURF1 is required to maintain low levels of DAB2IP in ovarian cancer." (PMID 38902547, 2024). "Finally, DAB2IP and RASAL2 mutations or deletions have been reported in different tumor types, including breast (both), gastrointestinal (DAB2IP), colorectal, lung, and ovarian cancer (RASAL2)." (PMID 33096593, 2020). "The lncRNA ATB binds to EZH2 and downregulates the expression of DAB2IP, CDH1, LATS2, FOXC1 and CDX1, thus facilitating the progression of ovarian cancer." (PMID 34890108, 2022).
abdominal aortic aneurysm (5 papers, 2013 to 2023). Enlargement and ballooning of the vessel that supplies arterial blood to the abdomen, pelvis and legs. "Recently, sequence variants in DAB2IP have been linked to aggressive metastatic prostate cancer, abdominal aortic aneurysms, and coronary heart disease." (PMID 23326475, 2013). "DAB2IP, encoding disabled homolog 2-interacting protein, which is involved in cell growth and survival and has been associated with aortic dissection as well as abdominal aortic aneurysms." (PMID 36561772, 2022). "Multiple variants in DAB2IP have been associated with CAD, and rs7025486 is associated with abdominal aortic aneurysm." (PMID 33171725, 2020). "Dab2IP regulates PI3K-AKT signaling and is associated with metastatic prostate cancer, abdominal aortic aneurysms and coronary heart disease." (PMID 23326475, 2013). "The present study shows that the single nucleotide polymorphisms (SNPs) of the genes CDKN2BAS rs10757278, LPA rs3798220, SORT1 rs599839, DAB2IP rs7025486, and IL6R rs2228145 are associated with the development of abdominal aortic aneurysms (AAA) in a study population." (PMID 37893562, 2023). "Importantly, human genome-wide association studies (GWAS) have identified DAB2IP, the gene for AIP1, as a susceptibility gene for early onset of myocardial infarction, abdominal aortic aneurysm, and peripheral vascular disease." (PMID 29731721, 2018).